ATG16L1 (autophagy related 16 like 1)
Diseases named in the same sentence as ATG16L1 in open-access papers (continued):
Sharing a sentence is not in itself a finding about the gene and the disease.
Crohn disease (continued). "In mice expressing a Crohn’s disease-associated risk polymorphism (ATG16L1T300A), secreted lysozyme is significantly decreased, suggesting that the dysfunction of the ER stress response and ATG16L1-dependent secretory macroautophagy etiologically are associated with Crohn’s disease." (PMID 37762105, 2023). "Deficiency in the autophagy gene Atg16l1 in combination with the persistent norovirus strain CR6 led to a significantly pronounced Crohn’s disease phenotype in the murine model of DSS-colitis, a phenomenon referred to as “Virus-Plus-Susceptibility Gene interaction”19." (PMID 34188111, 2021). "This provides a strong molecular basis for the contribution of vitamin D deficiency to the pathogenesis of Crohn's disease (CD) because the interaction of ATG16L1 and NOD2 participate in an autophagy‐dependent antibacterial pathway implicated in CD pathogenesis." (PMID 33559391, 2021). "NOD2 and ATG16L1 genetic variants that lead to reduced function are associated with Crohn disease." (PMID 31610723, 2019). "Understanding how ATG16L1 properly regulates NOD1/2 activation might pave the way to a better understanding of disease pathogenesis (e.g., for Crohn's disease patients bearing variants in ATG16L1)." (PMID 31803185, 2019). "Atg16L1 mutations have been found to be linked with Crohn’s disease." (PMID 31277291, 2019). "However, given the limited observations in our cases, further studies are required to understand the role of rare variants in ATG16L1 in Crohn’s disease." (PMID 30166421, 2018). "Moreover, ATG16L1 and nucleotide-binding oligomerization domain-containing protein 2 interact in an autophagy-dependent antibacterial pathway implicated in Crohn’s disease pathogenesis." (PMID 30108582, 2018). "ATG16L1 variant rs2241880, a nonsynonymous 898 T > C polymorphism that encodes a threonine-to-alanine change (T300A), is associated with a decreased autophagy in Crohn's disease and higher inflammation." (PMID 28761177, 2017). "ATG16L1 is a classic gene that is associated with the development of Crohn's disease." (PMID 25883416, 2015). "Hence, we aimed to examine the association between IL23R (L310P) and ATG16L1 (T300A) polymorphisms and inflammatory bowel disease (Crohn’s disease and Ulcerative colitis) in a cohort of Moroccan patients." (PMID 25159710, 2014). "Considering that Atg16L1 is an important gene in the development of Crohn’s disease, endotoxin-induced inflammasome activation in Atg16L1-deficiency could be involved in the occurrence of Crohn’s disease." (PMID 25009542, 2014). "Interestingly, NOD2 mutations and single-nucleotide polymorphisms in Atg16L1 are well-known features of Crohn’s disease." (PMID 25009542, 2014). "Importantly, a mutation in the Crohn’s disease susceptibility gene Atg16L1 promotes several hallmarks of the Crohn’s disease upon viral infection." (PMID 25437036, 2013). "Genetic studies have identified candidate loci for Crohn's disease susceptibility among autophagy genes, while experiments in murine macrophages from ATG16L1 deficient mice have shown that disruption of autophagy increases processing of IL-1β and IL-18 through an inflammasome-dependent manner." (PMID 21490934, 2011). "Mucosa from patients homozygous for the ATG16L1 Crohn's disease risk allele contained Paneth cells with similar alterations to those in ATG16L1 deficient mice including cells with disorganized or diminished granules or cells exhibiting altered cytoplasmic lysozyme staining." (PMID 21188215, 2010). "Thus, we propose that the association of ATG16L1*300A with increased risk of Crohn's disease is due to impaired bacterial handling and lowered rates of bacterial capture by autophagy." (PMID 18852889, 2008). "Notably, a polymorphism in ATG16L1 (T300A) is strongly linked to Crohn's disease susceptibility, suggesting that the role of ATG16L1 in this inflammatory disorder might be linked to VAIL rather than macroautophagy." (PMID 39145464, 2024).
Crohn disease (continued). "Furthermore, we have also seen that Crohn's disease patients that were homozygous carriers of the ATG16L1 T300A SNP responded better to thiopurine therapy than Crohn's disease patients that carried at least one wild-type (WT) ATG16L1 allele." (PMID 33973626, 2021). "Interestingly, increasing evidence has shown that NOD2 stimulation impairs autophagy response in dendritic cells and that increased activation of autophagy related 16 like 1 (ATG16L1) signaling upregulates the induction of deficient autophagy in Crohn’s disease." (PMID 33670592, 2021). "More specifically, Ruminococcaceae were enriched in CD patients of small intestine mucosa and often co-occurring with increased disease activity, which may also explain that the Atg16L1 T300A variant confers increased risk for the development of Crohn’s disease." (PMID 35154071, 2021). "ATG16L1 polymorphisms together with the excessive production of IL-1β and IL-6 in human peripheral mononuclear cells may account for the chronic inflammatory process in Crohn’s disease." (PMID 33020418, 2020). "Interestingly, ATG16L1 polymorphisms are also linked to Crohn's disease like NOD2." (PMID 31886308, 2019). "First, the Autophagy related 16-like 1 (ATG16L1) gene that maps to a Crohn’s disease susceptibility locus encodes a protein associated with depolarized mitochondria in response to mitophagy inducers, although its association with Crohn’s disease seems rather due to its function in xenophagy." (PMID 29971063, 2018). "Interestingly, Atg16L1 polymorphism has been recently associated with an excessive production of IL-1β and IL-6 in humans, further indicating the implication of autophagy in the pathophysiology of Crohn's disease." (PMID 22110539, 2012). "This difference has “real world” relevance as people homozygous for ATG16L1 A300/A300 are significantly more likely than those with ATG16L1 T300/T300 to present with Crohn’s Disease." (PMID 40827882, 2025). "For example, Atg16l1 T300A mice mimic human Crohn’s disease features, with fewer secretory granules and disorganized lysozyme." (PMID 40564109, 2025). "Among them, ATG16L1, NOD2, IRGM, and LRRK2 are autophagy-associated genes, which highlights the key role of autophagy in genetic susceptibility of Crohn's disease." (PMID 39883213, 2024). "Exaggerated IRE1α signaling appears to drive Crohn's disease‐like ileitis in mice, whereas ATG16L1‐dependent autophagy restrains IRE1α signaling pathway." (PMID 39188936, 2024). "Crohn’s disease-associated mutations in NOD2 and ATG16L1 render these proteins inactive for autophagy induction." (PMID 37425656, 2022). "Expression of ATG16L1 A300 predicts for a higher incidence of Crohn’s Disease in European Americans." (PMID 34252884, 2021). "In this paper, we have focused on the patients with Crohn's disease homozygous for the ATG16L1 T300A SNP, accounting for ∼30% of all patients." (PMID 33973626, 2021). "Recent advances in genetics have revealed that polymorphisms in autophagy-related 16-like 1 (ATG16L1) gene, which is essential for LC3 lipidation and autophagosome formation, are a genetic risk factor for Crohn’s disease." (PMID 34830679, 2021). "Further evidence that both pathways are interlinked is based on the observation that defective ATG16L1-mediated removal of IRE1α drives Crohn's disease like ileitis in the mouse." (PMID 32351509, 2020). "Norovirus infected mice with reduced ATG16L1 expression have decreased and disorganized Paneth cell granules and decreased lysozyme, and similar defects have been identified in Crohn’s disease patients." (PMID 32671059, 2020). "The role of Autophagy Related 16 Like 1 (ATG16L1) in Crohn’s diseases is even more well-characterized by a large body of literature (See26 for a comprehensive review)." (PMID 33293650, 2020). "Autophagy genes, such as ATG16L1, have been associated with inflammatory bowel disease (IBD), particularly Crohn’s disease (CD)." (PMID 32984329, 2020).
Crohn disease (continued). "For example, ATG16L1 was shown to be crucial for the cytokine responses by nucleotide binding oligomerization domain (NOD) and the disruption of NOD1- or NOD2-ATG16L1 signaling axis-mediated pro-inflammation in Crohn’s disease." (PMID 33013364, 2020). "Moreover, the autophagy gene ATG16L1 is essential in the intestinal epithelium for preventing the loss of Paneth cells and a variant of ATG16L1 is associated with poor survival in allogeneic hematopoietic stem cell transplant recipients and Crohn’s disease (CD), one of the two forms of IBD." (PMID 33050394, 2020). "In patients with Crohn's disease who are homozygous for the T300A substitution in ATG16L1, they have abnormal TLR signaling and Paneth cell function." (PMID 31886308, 2019). "Upon exposure to DSS in the drinking water, MNV-infected Atg16L1-mutant mice developed increased intestinal pathology in the colon and blunting of villi in the ileum resembling Crohn’s disease." (PMID 29570694, 2018). "Another noteworthy observation is that VDR was centred by MUC19, MST1, ATG16L1 and NOD2, which synergistically contributed to Crohn's disease risk." (PMID 29441677, 2018). "Decreased macroautophagy due to NOD2 and ATG16L1 mutations may impair innate resistance to invading bacteria and, thereby, trigger inflammation as a result of increased antigenic load or lead to insufficient tolerance induction against commensals in the gut and trigger Crohn’s disease." (PMID 29515999, 2018). "Autophagy-related protein 16-1 (ATG16L1) contributes a critical role in autophagy and ATG16L1 dysfunction leads to immune diseases such as Crohn’s Disease and decreased antibacterial defense." (PMID 29459719, 2018). "In one study, levels of MIR106B were found to be elevated in the intestinal epithelium of patients with active Crohn’s disease along with decreased levels of ATG16L1 transcripts." (PMID 30154791, 2018). "Amongst genes in SNP-associated bins, we found Crohn’s disease-associated genes STAT3, ATG16L1 and MHC genes HLA-DWB, HLA-DRA and HLA-DQA252." (PMID 29402885, 2018). "There are numerous genes that are involved in autophagy, including ATG16L1, NDP52, IRGM, and LRRK2 that have been found to be mutated in Crohn’s Disease patients; a number of these mutations also manifest with multiple clinical presentations." (PMID 29743550, 2018). "Moreover, the inhibition or impairment of ATG16L1 was associated with autophagy block and incapacity to control inflammasome proteolysis in autophagolysosomes resulting in exacerbated IL-1β secretion, inflammation and necrotic cell death in the context of epithelial cells and Crohn’s disease." (PMID 29326705, 2017). "Paneth cell dysfunction in both humans and mice is also associated with autophagy related 16-like 1 (ATG16L1) and X-box binding protein 1 (XBP1), both of which are associated with increased risk of Crohn's disease." (PMID 26484345, 2015). "For example, ATG16L1 mice infected with MNV CR6 exhibited multiple hallmarks of human Crohn’s disease after dextran sodium sulfate administration compared to mice infected with MNV-1 CW3." (PMID 26338794, 2015). "Our objective was to assess the frequency of ATG16L1 (T300A) and IL23R (L310P) variants in Moroccan IBD (Crohn’s disease and Ulcerative Colitis) patients and to evaluate a possible effect of these variants on disease’s phenotype and clinical course." (PMID 25159710, 2014). "Polymorphisms in ATG16L1 and NOD2 genes have been linked to Crohn's disease, an intestinal inflammatory disease." (PMID 24818040, 2014). "The role of NOD2 in these diseases has been illuminated by the identification of proteins, such as ATG16L1 and CARD9, which are both linked to Crohn's disease and interact with NOD2." (PMID 25520185, 2014). "Genome-wide association studies have shown association between single nucleotide polymorphisms (SNPs) in autophagy related gene 5 (Atg5), and Atg16l1 with susceptibility to systemic lupus erythematosus (SLE) and Crohn’s disease, respectively." (PMID 23596443, 2013).
Crohn disease (continued). "In our AD EA TWAS, we also identified genes associated with other neurological and autoimmune diseases, including Parkinson’s disease (CYB561 and SLC25A39), Crohn’s disease (ATG16L1), Amyotrophic lateral sclerosis (SIGLEC9), and Riboflavin Transport Deficiency (SLC52A1)." (PMID 40141087, 2025). "CASM-dependent LRRK2 activation may also be relevant for Crohn’s disease, where human genetics has established roles for both ATG16L1 and LRRK2, and our data now place these genes into a common cellular pathway." (PMID 39812709, 2025). "It appears that exaggerated IRE1α signaling may be a driving force in Crohn's disease‐like ileitis mouse model, whereas ATG16L1‐dependent autophagy seems to exert a restraining influence on IRE1α signalling." (PMID 39188936, 2024). "Consequently, Paneth cell biology and distinct regulatory characteristics are modulated by ATG16L1, which in turn affects the intestinal epithelium of Crohn's disease patients." (PMID 39883213, 2024). "Moreover, it has been found that ATG16L1 and NOD2 both support the autophagy-dependent antimicrobial pathway, which is modified by Crohn's disease-associated mutations in a way that is specific to certain cell types." (PMID 39883213, 2024). "In ATG16L1‐deficient mice, MNV infection leads to a phenotype resembling Crohn's disease." (PMID 39287214, 2024). "This capacity relies on the direct interaction of C3 with ATG16L1 and is altered in cells lacking ATG16L1 or carrying its T300A variant that is associated with Crohn’s disease." (PMID 37425656, 2022). "Another notable results from the MSEA found microbes with differential abundance in Crohn’s disease are enriched for microbes associated with ATG16L1, CCL11 and FUT2, all of which have been implicated in the pathology of Crohn’s diseases, an inflammatory bowel disease (IBD)." (PMID 33293650, 2020). "Targeting of autophagy protein, ATG16L1, by miR142-3p suggests that this miRNA may play a role in intestinal inflammation and Crohn’s disease." (PMID 33020418, 2020). "Most importantly, however, it was demonstrated in Crohn's disease patients that genetic variants synthesize to produce Paneth cell phenotypes of Crohn's disease: i.e., the granule defects were more pronounced it the patient carried multiple NOD2 and ATG16L1 risk genes." (PMID 32351509, 2020). "For instance, genetic studies have demonstrated that the immunity-related GTPase family M protein (IRGM) and autophagy related 16 like 1 (Atg16L1), which are two proteins involved in autophagy pathways, are involved in the inflammatory syndrome Crohn’s disease." (PMID 32604771, 2020). "Together these data suggest that autophagy is a key pathway linking NOD2 and ATG16L1 in the development of Crohn’s disease and hint that XIAP may also have some role in autophagy regulation." (PMID 29743550, 2018). "Since proper function of ATG16L1 is necessary for host-defense responses against micro-organisms and inflammatory responses in Crohn’s disease, this gene might be relevant in the respiratory system as well." (PMID 30390659, 2018). "Importantly, DCs expressing the Crohn’s disease NOD2 and ATG16L1 variants have reduced autophagic response and MHC class II antigen presentation in response to MDP." (PMID 29515999, 2018). "Interestingly, miR-106b was described as the posttranscriptional target of the autophagy-related gene 16L1 (ATG16L1) regulating autophagy in the context of epithelial cells and Crohn’s disease." (PMID 29326705, 2017). "It is interesting to note that the same mutation occurs in some cancer samples and so reduced activity of ATG16L1 may have functional consequences in other diseases as well as Crohn's disease." (PMID 27256984, 2016). "Atg5 −/− or Atg7−/− mice or mice hypomorphic for Atg16L1 exhibit intestinal Paneth cell abnormalities resembling Crohn’s disease, which may results in intestine cancer." (PMID 25844158, 2015).
Crohn disease (continued). "In addition, a truncated version of NOD2 found in some patients with Crohn's disease cells leads to the retention of ATG16L1 in cytoplasm, inhibiting its recruitment to plasma membrane and reducing autophagic activity." (PMID 24818040, 2014). "The role of autophagy in inflammatory diseases was initially established through genome-wide association studies (GWAS) showing that polymorphisms in autophagy-associated genes, such as ATG16L1 and IRGM, are linked to Crohn’s disease, the well-known inflammatory bowel disease." (PMID 25169902, 2014). "Genetic studies have identified allelic variants of the autophagy genes ATG16L1 (autophagy related 16-like 1) and IRGM (immunity related GTP-ases, M) as important risk factors for Crohn's disease, an autoinflammatory disease characterized by severe chronic inflammation of the gut mucosa." (PMID 21490934, 2011). "ATG16L1 could be targeted by miR-142-3p, a novel miRNA that regulates autophagy in human colonic epithelial cells, suggesting the role of miRNA-mediated regulation of ATG16L1 in intestinal inflammation and Crohn disease." (PMID 35524319, 2022). "Using ATG16L1 knockdown constructs in vitro that reduced the ATG16L1 protein levels to a similar degree as seen in homozygous ATG16L1 T300A carriers, we aimed to elucidate part of the mechanism that makes homozygous carriers prone to developing Crohn's disease." (PMID 33973626, 2021). "The remarkable restoration of the wound-healing capacity of the HT29 ATG16L1 knockdown cell lines treated with 6-TG may be important in the increased potential of thiopurines in ATG16L1 T300A homozygous Crohn's disease patients compared to ATG16L1 WT Crohn's disease patients." (PMID 33973626, 2021). "Genetic variations in genes encoding for autophagy-related 16-like 1 (ATG16L1), Unc-51-like autophagy-activating kinase (ULK1), immunity-related GTPase family M protein (IRGM) and nucleotide-binding oligomerization domain-containing protein 2 (NOD2) have all been associated with Crohn's disease." (PMID 33973626, 2021). "Interestingly, the interaction between ATG16L1 and A20 is not altered by the T300A allele that increases the risk for Crohn’s disease." (PMID 31015422, 2019). "In humans, single nucleotide polymorphisms (SNPs) in the autophagy-related protein 16-like 1 (atg16l1) gene have been linked with increased susceptibility to Crohn’s disease, while Mice lacking Atg16L1 in hematopoietic cells are more susceptible to dextran sulfate sodium (DSS)-induced colitis." (PMID 23577011, 2013). "Interestingly, autophagy genes ATG16L1 and IRGM appear to be more specific for Crohn's disease and IRGM risk alleles may predispose even more specifically to the ileal form of Crohn's disease." (PMID 21188215, 2010). "Susceptibility loci related to intestinal macrophage functions have been unraveled in Crohn’s disease patients, including NOD2, ATG16L1, CX3CR1, IL12p40, IL23R, JAK2, STAT3, and protein tyrosine phosphatase non-receptor type 2 (PTPN2)." (PMID 39095853, 2024). "In another study in humans, to understand the pathogenesis of Crohn’s disease, an R protein homolog, the cytosolic NOD1 and NOD2 receptors interacted with ATG16L1 to initiate autophagy of bacteria entering the host cell." (PMID 37936940, 2023). "The abnormality of ATG family proteins such as autophagy related 16 like 1 (ATG16L1) and ATG7 leads to the defects in AMPs expression in PCs from mice and Crohn’s disease patients." (PMID 36969191, 2023). "GWAS have identified ATG16L1 and immunity-related IRGM in Crohn’s disease, indicating a role of autophagy in the pathogenesis of IBD." (PMID 30108582, 2018). "One hundred fourteen participants from the general population were genotyped for ATG16L1 (T300A) and IL23R (L310P) along with 69 Crohn’s disease patients (25 women and 44 men) and 30 UC patients (14 women and 16 men)." (PMID 25159710, 2014).